TNF (tumor necrosis factor)
Diseases named in the same sentence as TNF in open-access papers (continued):
Sharing a sentence is not in itself a finding about the gene and the disease.
infection (continued). "As expected, Mab infected MDM showed a significant increase in TNF-α at 3 hrs after infection in comparison with uninfected macrophages, and PS-L treatment reduced the levels of the cytokine both in uninfected and infected cells, irrespective of CFTR inhibition." (PMID 39224705, 2024). "In addition, NAg can inhibit interferon-mediated immunity in the first days of infection and the subsequent release of proinflammatory cytokines, including IL-6, IL-1β, and TNF-α." (PMID 38535062, 2024). "Similarly, TNF-α levels were decreased across all OMT dosages at 36 h post-infection compared with the virus group (p < 0.05), further confirming OMT’s anti-inflammatory capacity." (PMID 38731436, 2024). "In addition, quercetin can inhibit the exaggerated inflammatory response following infection via subsiding the expression of TNF-α, IL-1β, and IL-6 in macrophages." (PMID 39575436, 2024). "Compared to the non-infection group, we observed elevated levels of the majority of measured cytokines (25/48) in the CSF during Mtb infection, including TNF-α, IFN-γ, IL-1β, IL-2, IL-3, IL-6, IL-8, IL-10, IL-12(p40), IL-17A, IL-18, IP-10, MIG, MCP-3, MIP-1α, and MIP-1β." (PMID 38047697, 2024). "Endotoxins can trigger inflammatory responses upon infection, releasing cytokines like interleukin-8 (IL-8) and tumor necrosis factor-alpha (TNF-α), which may induce shock." (PMID 38674716, 2024). "Blockade of TNF-α signaling protected LysM Cre+Ifnarflox/flox mice from lethal infections." (PMID 38550855, 2024). "The infection decreased significantly the levels of TNF-α and IFN-β induced by OMVs pre-treatment." (PMID 38533334, 2024). "When the organism is subjected to infection, tissue damage, or other pathological conditions, cells may release more TNF-α." (PMID 39582887, 2024). "TNF-α plays an important role in inflammation during infections and autoimmune diseases." (PMID 38716051, 2024). "Here, we demonstrated that macrophages derived from Smurf1−/− mice secreted increased levels of the proinflammatory mediators TNF and CXCL1 in vitro, and the lungs from Smurf1−/− mice presented higher ratios of macrophages and neutrophils positive for TNF and iNOS upon infection with MHV-A59." (PMID 39452742, 2024). "Furthermore, CD8+ T cells also produce cytokines such as IFNγ and TNF, which recruit neighbouring immune cells to the site of infection to assist in viral clearance." (PMID 38362528, 2024). "Importantly, the attenuation of Del4L was associated with a significant increase in the production of IL-1β and TNF-α early in the infection of pigs." (PMID 38501350, 2024). "TNFα and IL-6 were significantly raised in right vagotomized mice at days 3 and 8 post-infection, respectively, and left vagotomized mice showed an increase in IFNγ at day 8 post-infection." (PMID 38626267, 2024). "TNF-α promotes the production of other proinflammatory cytokines, such as IL-1β and IL-6, and induces the expression of adhesion molecules and chemokines, which attract immune cells to the site of injury or infection." (PMID 38397895, 2024). "Furthermore, large cohort studies have revealed elevated levels of IL-1β, IL-6, and TNF in the serum of clinical patients with an average period of 8 months after infection." (PMID 38299028, 2024). "Moreover, TLR2 ‘Agonist’ Pam3CSK4 improved the ratio of IL10/ TNFα which known to be protective against infection." (PMID 39729468, 2024). "Increased production of TNF-α and IL-12 during infection in the presence of IL-10 neutralizing antibodies further supports the hypothesis and paves avenue to explore the interdependency of IL-33 and IL-10." (PMID 38750790, 2024).
infection (continued). "In previous studies, some anti-inflammatory drugs, such as canakinumab (a fully human monoclonal antibody targeting the IL-1β) and methotrexate (a systemic anti- inflammatory drug targeting TNF-α), were limited in clinical practice by frequent infection events." (PMID 38988665, 2024). "Infection with ZIKV including MR766 induces inflammatory cytokines such as TNF-α, IL-6 and IL-1β." (PMID 39178324, 2024). "However, infection with the ΔprrH/Vector, ΔexsA/Vector, and the ΔexsA/PrrH strains suppressed the expression of TNF-α and IL-1β." (PMID 38289930, 2024). "Furthermore, our study revealed a significant 3-fold increase in TNF-α expression with the P. gingivalis and F. nucleatum co-culture infection." (PMID 38612423, 2024). "However, sustained synthesis of TNF-α can augment disease severity and lead to tissue damage in the later stages of infection." (PMID 39766307, 2024). "In addition, TNF‐α inhibitors have proven highly effective in reducing inflammation in AS patients, with the response to these inhibitors potentially influenced by infection‐related and metabolic pathways." (PMID 39031474, 2024). "TNF-α and IL-1β are proinflammatory cytokines involved in the induction of inflammatory reactions and both are released primarily by macrophages and monocytes during cell infection and inflammation." (PMID 38478426, 2024). "The results demonstrated that, influenced by the liver parasitic infection, pro-inflammatory factors IL-1β and TNF-α exhibited continuous increases in both serum and liver levels at all infection stages, while anti-inflammatory factors IL-4 and IL-10 showed persistent decreases." (PMID 39749332, 2024). "In the normal CNS, TNF expression is low and localized mainly to microglia, astrocytes, and neurons, but is markedly elevated during and after injuries (e.g., ischemia, trauma, and infection) due to secretion mainly by microglial cells." (PMID 38339126, 2024). "Continuously high concentrations of serum TNFα and IL-6 at the early infection course, as well as low IL-10, were detected in lnc-ip65−/− mice, suggesting that excessive inflammatory responses occurred and might contribute to the lethal pathogenesis." (PMID 38200007, 2024). "The current study also showed a higher host immune cytokine (TNF-α and IL-6) response in the oral cavity and uterus as a result of the polymicrobial infection compared to the CTL, indicating a local and systemic inflammatory response to the microbes and microbial products." (PMID 39203489, 2024). "Moreover, treatment with TAK-242 reduced M1_like and slightly increased M2_like macrophages and reduced pro-inflammatory cytokines levels including TNF, IL-1β and IL-6 in ECSparcl1-OE mice on day 20 after infection." (PMID 38762489, 2024). "Moreover, it is worth noting that the concomitant use of glucocorticoids has been associated with severe adverse reactions and interruption of some biologics such as anti-TNF agents and anti–IL-6 agents, mainly owing to infection." (PMID 39886456, 2024). "Furthermore, it has been discovered that TP4 therapy decreases inflammatory cytokines at the infection site, including TNF and IL-6, and regulates epidermal healing by regulating fibroblast and keratinocyte proliferation and differentiation." (PMID 38741875, 2024). "Furthermore, macrophage infection assays using RAW264.7 cells revealed that isolates from clade I induced inflammatory cytokine expression (TNF-α and IL-6) at levels comparable to those observed in isolates from other clades." (PMID 39530695, 2024). "TNF-α and IL-1β play an important role in the clearance of bacteria and viruses during early infection, but their overproduction could trigger an inflammatory storm, which damages tissues and organs." (PMID 39408834, 2024). "A low level of TNF-alpha activated defense system to prevent an invasion of infection." (PMID 38997754, 2024).
infection (continued). "Of note, RNAi-mediated depletion of DDB1 and TAK1 impaired TNF release after infection with Vpr null virus, suggesting that infection-stimulated TNF release may be another physiological function of DDB1 that is enhanced by HIV-1 Vpr." (PMID 39205287, 2024). "The efficiency with which AN_CH_37 treatment suppressed the pro-inflammatory response suggests that Mip supports potent stimulation of IL-1β, TNFα and IL-6, and thus may play an important role in host inflammatory pathology following infection." (PMID 38590438, 2024). "Moreover, TNFα expression was significantly higher in lean mice on the first day post-infection and reversed on day 5 post-infection." (PMID 39590816, 2024). "Moreover, IL-6 and TNF-α enable augmentation of inflammatory cells in areas of local infection, increasing the effects of other cytokines and inflammation." (PMID 38611807, 2024). "Cytokines released by infection, such as IL-1, TNFα and IL-6, will activate the HPA axis, and the endogenous cortisol level in those with preserved adrenal function will increase significantly at this time to inhibit inflammatory cytokines and reduce inflammatory response." (PMID 39741879, 2024). "Inflammatory cytokines such as tumor necrosis factor-alpha (TNF-α), and interleukin-6 (IL-6) act as potent chemoattractant, effectively facilitating the recruitment and mobilization of immune cells towards the precise location of infection." (PMID 38997643, 2024). "In fact, they could possibly mitigate the increased expression level of TNFα in hippocampus produced by microglia and astrocytes in response to the infection." (PMID 39959586, 2024). "Cytokines such as IFN-γ, IL-10, TGF-β, TNF-α, and IL-17, among others, play a crucial role in regulating the expression of chemokines and chemokine receptors on immune cells, ultimately shaping the cellular landscape at the site of infection." (PMID 39587036, 2024). "This insight is consistent with our immunohistochemical findings, wherein we observed intense TNF-α immunoexpression, one of the key mediators of inflammation, in the lung, remaining elevated primarily in the Wuhan group across different post-infection periods." (PMID 39211479, 2024). "Our data indicated that fat loss significantly increases TNFα levels and does not alter IFNγ levels in both males and females compared to RD-fed mice during infection." (PMID 38999932, 2024). "Similar to infection-induced inflammation, sterile inflammation is characterized by the recruitment of immune cells and the secretion of proinflammatory cytokines and chemokines, especially tumor necrosis factor (TNF-α) and IL­1β." (PMID 39343901, 2024). "Interestingly, infection of Calu-3 cells with WT triggered a significantly higher secretion of TNF-α and IL-6 than galU−." (PMID 38470050, 2024). "After BoDV1 infection of TNFTg mice, peroxisomal and catalase abundances did not change in neuronal cells from transgenic brain areas, suggesting that mild chronic TNF pre-sensitization of neurons in vivo counteracted changes in peroxisomal and catalase abundance after BoDV1 infection." (PMID 38339126, 2024). "IL-10–mediated inhibition of shedding GC-associated cervical epithelial cells in the presence of the potent inflammatory cytokines IL-1β and TNF-α underscores the importance of the direct interaction of IL-10 with IL-10R on epithelial cells for GC-establishing infection at the human cervix." (PMID 39585777, 2024). "In contrast with IL-4, IL-5, and IL-13, mRNA expression of IL-1β and TNF-α, both considered type 1 cytokines, decreased after infection with RV2, suggesting that RV infection on day 6 of life skewed the response to subsequent heterologous RV infection toward a type 2 phenotype." (PMID 38061015, 2024). "It remains controversial whether the five TNF inhibitors are different in terms of infection incidence." (PMID 39070789, 2024).
infection (continued). "Similarly, it was found that the presence of comorbidity, especially of cardiovascular disease, was a better indicator of serious infections during anti-TNF-α antibody therapy compared to patients’ age." (PMID 38792308, 2024). "Therefore, we assessed the mRNA expression levels of the key inflammatory cytokines TNF, IL-6, and IL-1β following 6 h post-infection with S. anginosus or S. mitis by qPCR and supernatant protein levels following 24 h of infection by ELISA." (PMID 38289109, 2024). "Meanwhile, TNFα or IL-6 levels decreased in 10aa−/− mice post-infection." (PMID 39519103, 2024). "Importantly, macrophages and DCs are natural sources of TNFα that trigger apoptosis in an autocrine fashion after infection with mCMV-ΔM36." (PMID 39146364, 2024). "Interestingly, higher IL-6 and TNF-α levels were observed in BCG-infected mice after 90 days of infection as compared to Ms_Vc and Ms_Rv1509." (PMID 38803374, 2024). "We also detected lower TNF and IL-6 release after infection with R77Q vs. WT." (PMID 39459974, 2024). "Importantly, Del4L infection decreased the ubiquitination-mediated degradation of IκBα induced by TNF-α in contrast with ASFV-WT infection." (PMID 38501350, 2024). "This is likely due to the timing of samples as TNF-alpha is one of the very first pro-inflammatory cytokines to appear after infection, but it has also been found that TNF-α mRNA and other pro-inflammatory cytokines were inhibited by ASFV infection, both in vitro and in vivo in wild boars." (PMID 38658979, 2024). "Infection‐mediated release of inflammatory cytokines, such as IL‐6 and TNF‐alpha, could further damage the disc, leading to disc degeneration and a pro‐inflammatory environment." (PMID 39398942, 2024). "Finally, infection by S. mansoni led to an increase of TNF-α mRNA in the livers of C57BL/6 mice at 7 wpi, compared to Swiss and BALB/c mice." (PMID 38896633, 2024). "The innate and acquired immunity are regulated by TNF-α, an essential pro-inflammatory cytokine that controls the inflammatory response at the early stages of infection and activate phagocytes and macrophages, which in turn enhanced the activity of destroying microorganisms." (PMID 39794982, 2024). "Indeed, Ad-shBDNF-infection enhanced the expression of tumor necrosis factor α (TNFα), and its regulated gene IL-6 in C2C12 myotubes and the muscle of MBKO mice." (PMID 39531828, 2024). "TNF-α is a pro-inflammatory cytokine that can recruit leukocytes to areas of infection." (PMID 38473133, 2024). "However, this protocol resulted in a higher level of active infection in the 37°C untreated condition that reduced the apparent effect of TNF-α stimulation." (PMID 39636695, 2024). "Indeed, anti-TNF therapy reduced mortality in the LPS model, whereas TNF turned out to be essential for controlling the infection in the CLP model." (PMID 39456859, 2024). "Additionally, we observed 6.4-fold higher TNF-α expression during infection with the GI.1 genotype compared to the GI.2 infected group (p = 0.04)." (PMID 39273479, 2024). "Furthermore, another study showed that human M1-activated monocyte-derived macrophages stimulated less CCL3/MIP-1⍺ and less TNF-α after infection with lactate-grown C. albicans compared to glucose-only-grown cells." (PMID 38967888, 2024). "Here, we show that in mice, V. vulnificus secreting a MARTX toxin harboring the RDTND-RID effector duet significantly depletes NAD(P)+ levels and suppresses production of pro-inflammatory cytokines (including TNF-α) by downregulating ROS generation within 2 h post-infection." (PMID 39043696, 2024). "TNF-α attaches to endothelin cells and improves vascular permeability, allowing circulating neutrophils and monocytes to be recruited by inflammatory cytokines into the site of infection." (PMID 39845975, 2024).
infection (continued). "Tumor necrosis factor alpha (TNF-α), an inflammatory cytokine, mediates apoptosis in response to infection or injury, and a study demonstrated that EMD could reduce TNF-α-induced apoptosis similarly to the effects seen with TGF-β." (PMID 39337872, 2024). "In conclusion, the results of this study demonstrate that the assessment of a combination of IFN-γ and TNF-α may enhance the sensitivity of the IGRA test in dogs to diagnose infection with M. bovis." (PMID 39860978, 2024). "Moreover, hRSV-infected astrocytes produced IL-4, IL-10, and TNF-α during the first hours of infection and IL-6 in late times." (PMID 39203555, 2024). "Notably, infection with a high viral dose lowered blood glucose levels, which was dependent on cytokines such as IL-1β, IL-1α, IFNγ and TNF and proposed to be the result of hyperinsulinemia." (PMID 39107476, 2024). "Similar to TNFα, IL-1 signaling regulates a variety of inflammatory responses following infection." (PMID 39474417, 2024). "Finally, TNF-α was present in lower levels, probably because the serum was collected in the postacute phase of the infection." (PMID 39583156, 2024). "Interestingly, NHNE were able to re-activate pro-inflammatory responses towards the end of the 14-day infection, resulting in release of IL-8 and TNFα." (PMID 38990812, 2024). "Moreover, TNF‐α not only triggers the inflammatory response but also directly inhibits the proliferation of C. difficile, thereby mitigating infection." (PMID 38898983, 2024). "Dramatic reductions in leukocyte recruitment were observed in TNF KO mice in a time-dependent manner, where granulocytes were significantly decreased uniformly in the brain, galea, and bone flap of TNF KO mice at day 14 post-infection, both by relative abundance and absolute count." (PMID 39044282, 2024). "The p38 signaling transduction pathway (a mitogen-activated protein kinase pathway), plays an important role in modulating the immune response of the host by coordinating the release of pro-inflammatory cytokines such as interleukin (IL-1β) or tumor necrosis factor (TNF) upon infection." (PMID 38674369, 2024). "During infection, proinflammatory Ly6Chi monocytes are recruited into the site of inflammation, where they differentiate into inflammatory macrophages that produce high levels of inflammatory cytokines such as IL-6, TNF-α, IL-1β." (PMID 38646937, 2024). "However, 24 h post-infection treatment with 0.5 mM butyrate had significantly increased TNF-α secretion (1.5-fold, P=0.0032)." (PMID 39392674, 2024). "Furthermore, the absence of the IL-22 cytokine exacerbates lung inflammation, resulting in significantly elevated levels of IL-1β, TNF-α, and IL-12 during infection." (PMID 39635124, 2024). "IL6 and TNF were significantly upregulated in VRI_stage1 and VRI_stage2, contributing to the inflammatory response, and it was observed that they were upregulated in both basal and secretory cells at 28 dpi, which is a considerable time after infection." (PMID 39735182, 2024). "The cytokine expression of TNF-α and IL-1β was significantly reduced at 12 h and 24 h post infection of cells treated with LPS isolated from JOL2943, whereas in Hela cells, LPS isolated from JOL2943 induced significantly low TNF-α at 24 hpi and IL-1 at 12 h and 24 hpi." (PMID 38474006, 2024). "Indeed, it was found that in patients previously hospitalized for infection while receiving anti-TNF agents, both ABA an ETN have a lower risk of subsequent infection compared to other biologics." (PMID 38979406, 2024). "Inflammation during malaria infection occurs due to the release of proinflammatory molecules including interleukin (IL)-1β, IL-6, IL-8, IL-12 (p70), interferon (IFN)-γ, and tumor necrosis factor (TNF), which are released to slow down parasite growth and eliminate the infection." (PMID 39569379, 2024).